TIGAR (TP53 induced glycolysis regulatory phosphatase)
Diseases named in the same sentence as TIGAR in open-access papers (continued):
Sharing a sentence is not in itself a finding about the gene and the disease.
cancer (continued). "TIGAR is a protein that can augment antioxidant capacity, and while TIGAR is not required for normal growth and development, it is overexpressed in many human cancers." (PMID 39636862, 2024). "It is well accepted that downregulation of BRCA1 and BRCA2 leads to PARP inhibitor sensitivity, and our data suggest that TIGAR KD induces “BRCAness” by phenocopying the gene expression pattern produced by BRCA1/2 downregulation and thereby sensitizes cancer cells to olaparib." (PMID 31508509, 2019). "In addition, our results indicate that knockdown of TIGAR reduces the expression of MMP2 and MMP9, which play important roles in the formation of tumor microenvironments and in the promotion of cancer progression and metastasis." (PMID 29753331, 2018). "Given the activities of TIGAR in lowering ROS and promoting anabolic pathways, and the contribution of these pathways to cancer development, it is perhaps not surprising that overexpression of TIGAR has been described in a number of tumor types." (PMID 24383451, 2014). "On basis of the existing literature and the cellular outcomes observed upon upregulation of TIGAR and SCO2 in cancer cells, the cellular conditions which might lead to the synthesis of these genes can be predicted." (PMID 22248668, 2011). "Accordingly, we observed significant suppression of cancer cell proliferation and colony formation ability when AMPK or GLS expression was knocked down or the activity was inhibited, and the suppression effect was much stronger in cells with TIGAR overexpression." (PMID 32206103, 2020). "Therefore, we postulated that TIGAR, as a key regulator of PPP, may be involved in the development of cancer metastasis." (PMID 29753331, 2018). "Under normoxia, TIGAR downregulates glycolysis flux because it decreases the F2,6BP level, which is a potent allosteric activator of PFK-1 in cancer and noncancer cells." (PMID 31600993, 2019). "In addition to the difference between cultured cancer cells and in vivo tumor environment, the reported adaptation in TIGAR expression from acute to chronic conditions could contribute to the lack of TIGAR induction in tumors of Caki-1 cells stably transfected with shPFKP1." (PMID 27049827, 2016).
tumor (68 papers, 2009 to 2025). "TIGAR, an enzyme involved in glycolysis and a participant in antioxidant responses, often associates with an aggressive tumor phenotype and plays a crucial role in establishing resistance to chemotherapies." (PMID 40277923, 2025). "For instance, ROS derived from NADPH oxidase can promote tumor cell proliferation, while ROS resulting from TIGAR deficiency have the opposite effect." (PMID 40699802, 2025). "Univariate Cox regression analysis revealed that factors such as T stage (p < 0.001), M stage (p = 0.017), pathologic stage (p < 0.001), tumor presence (p < 0.001), and TIGAR expression (p < 0.001) are linked to poor prognosis for HCC." (PMID 39091612, 2024). "On the other hand, loss of TIGAR and the increasing production of mitochondrial ROS enhanced the metastatic capacity of the tumour cells." (PMID 33941245, 2021). "Increased TIGAR expression was associated with patients that older than 60 years old (P=0.044), with venous tumor thrombus (P=0.026), and with higher SUVmax (P=0.024)." (PMID 31892967, 2020). "In brief, PanINs and tumor proliferation is associated with higher expression of TIGAR and low levels of ROS." (PMID 33198082, 2020). "Taken together, these results show that increased ROS in response to loss of TIGAR can promote a mesenchymal shift accompanied by increased invasive capacity, but that modulating ROS levels can allow the tumor cells to toggle between the two phenotypes." (PMID 31983610, 2020). "In an in vivo model of intestinal adenoma where adenomatous polyposis coli (APC) is deleted in LGR5+ intestinal stem cells, TIGAR deficiency decreases tumour burden and average tumour size, which results in increased disease-free survival in these mice." (PMID 25243985, 2015). "A similar contribution of TIGAR to tumor progression was also observed in the colon, and importantly, the decrease in tumor burden observed in TIGAR-deficient mice correlated with a greater survival in these mice." (PMID 24383451, 2014). "In an intestinal adenoma model where APC is deleted in LGR5+ intestinal stem cells, mice deficient in TIGAR showed a reduction in total tumor burden and average tumor size in the small intestine compared to wild-type mice." (PMID 24383451, 2014). "Although TIGAR is closely linked to glucose uptake in tumor tissues, there have been few reports on its relationship with the biological characteristics of tumor tissues." (PMID 24363807, 2013). "High TIGAR expression is associated with aggressive tumor behavior and poor patient prognosis." (PMID 39091612, 2024). "To test directly whether loss of TIGAR and ROS regulation could have an impact on metastatic capacity, we turned to an experimental model of metastasis in which lung colonization of tumor cells following tail vein injection was assessed." (PMID 31983610, 2020). "Next, to explore whether TIGAR was causally involved in the tumor progression of GC, we knocked down TIGAR expression using two shRNAs (shTIGAR B5, shTIGAR B6) in two GC cell lines (AGS and SGC7901)." (PMID 31799200, 2019). "The elevated levels of TIGAR expression in some types of tumors and the action of different therapeutic agents associated with decreased TIGAR expression, highlight the importance of TIGAR in tumor cell survival." (PMID 30234009, 2018). "High expression of TIGAR was also associated with tumor progression." (PMID 29753331, 2018).
tumor (continued). "Given that the involvement of TIGAR within these cellular processes may promote tumor progression, further investigations that examine how TIGAR supports NPC tumor growth, and the associated molecular pathways, are warranted." (PMID 25621025, 2015). "In addition, the reduced tumor burden was correlated with an improved survival rate of the TIGAR-deficient mice." (PMID 25621025, 2015). "Tumour intestinal crypts isolated from these mice showed that the in vitro growth of the TIGAR- deficient tissues can be rescued by the addition of antioxidants and nucleosides, again indicating an important role of TIGAR in increasing PPP during proliferation." (PMID 25243985, 2015). "Furthermore, in a mouse model of intestinal adenoma, TIGAR-deficient mice exhibited reduced adenoma size and tumor burden compared with wild-type mice." (PMID 25621025, 2015). "Indeed, using conditionally expressed TIGAR alleles, TIGAR loss was beneficial subsequent to tumor establishment, providing some indication that TIGAR may be a useful therapeutic target." (PMID 24383451, 2014). "Immunohistochemical analysis of TIGAR at various stages of PDAC tumorigenesis shows an increase in TIGAR expression during the early stages of tumor progression in both the KFC mouse model and human PDAC samples." (PMID 40277923, 2025). "This suggests TIGAR’s inhibition as a strategy to sensitize hrHPV+ tumor cells to chemotherapy agents." (PMID 40277923, 2025). "Gene expression analysis using the RNA-seq database revealed higher TIGAR mRNA expression in tumor samples compared to the corresponding normal tissues (p < 0.05) based on the Wilcoxon rank sum test." (PMID 39091612, 2024). "Specifically, TIGAR exhibits higher expression in tumor samples and N0 and N1 samples compared to normal samples." (PMID 39091612, 2024). "TIGAR overexpressing KPC-Tg tumor cells showed a lower ability to attract macrophages compared to KPC cells." (PMID 39636862, 2024). "Utilizing a Cox regression model, we demonstrated that TIGAR, along with factors such as T stage, M stage, pathologic stage, and tumor presence, correlated with a poor prognosis for HCC." (PMID 39091612, 2024). "Studies have also hinted at TIGAR’s potential involvement in the regulation of cell cycle, proliferation, invasion, and metastasis-related proteins in tumor cells." (PMID 39091612, 2024). "Through the application of the Spearman correlation method, we examined the relationship between TIGAR expression levels and immune infiltration in the tumor microenvironment, using ssGSEA for our analysis." (PMID 39091612, 2024). "Our findings shed light on the complex interplay between TIGAR expression and immune cell infiltration within the tumor microenvironment, providing valuable insights into the mechanisms underlying HCC development and progression." (PMID 39091612, 2024). "As an ROS restriction protein, TIGAR is highly expressed in tumor cells, exerting antioxidant effects by regulating NADPH production via the pentose phosphate pathway." (PMID 39091612, 2024). "We have used modulation of TIGAR in genetically engineered PDAC mouse models to investigate the impact of tumor-derived ROS on stromal cells in the tumor microenvironment (TME)." (PMID 39636862, 2024). "This contributes to developing our understanding of the mechanism of action of the TIGAR in the tumor metabolism." (PMID 36555672, 2022).
tumor (continued). "Increasing evidence shows that the TIGAR is an important regulator of tumor development and sensitivity to chemotherapy, radiotherapy, targeted therapy, and endocrine therapy." (PMID 36555672, 2022). "TIGAR-encoded protein can degrade fructose 2,6-diphosphate, which is the strongest activator of the key enzyme PFK1 in the glycolytic pathway of tumor cells." (PMID 34975319, 2022). "Several studies have shown that expression levels of TIGAR are high in tumor samples from different origin." (PMID 35163828, 2022). "Expression of NRF2 and TIGAR is required for tumor initiation and for the development of established metastases, however loss of either one of these genes leads to increased ROS and metastatic potential." (PMID 35163828, 2022). "In physiological conditions, TIGAR expression confers cytoprotection and can prevent tumor development, as shown in mouse intestinal epithelia." (PMID 35163828, 2022). "As a suppressor of glycolysis, however, the exact role of TIGAR as a tumor enhancer or suppressor is controversial." (PMID 33946927, 2021). "Upon reaching the secondary site, CSCs would switch back to higher TIGAR expression with the accompanying metabolic state with low ROS that would be more compatible with cell proliferation and tumour growth." (PMID 33941245, 2021). "Among patients, positive TIGAR expression was found in tumor tissues of 38 patients (61.29%), while the rest 24 patients (38.71%) have negative TIGAR staining." (PMID 31892967, 2020). "For example, in HCC, miR-885-3p and miR-766 played a role in tumor progression by targeting TIGAR and NR3C2, respectively." (PMID 33221765, 2020). "It seems likely that DUSP6 expression can be fine-tuned to modulate ERK at different stages of tumor progression and that this ability is lost in TIGAR null cells." (PMID 31983610, 2020). "Previous studies have suggested that TIGAR plays a role in tumor progression by regulating tumor burden and redox homeostasis." (PMID 31892967, 2020). "The expression of MUC1‐C and TIGAR in tumor tissue and normal tissues were investigated using immunohistochemistry." (PMID 30523643, 2019). "In the present study, we reveal that TIGAR was highly expressed in primary GC samples, which protected tumor cells from oxidative and metabolic stresses, and TIGAR depletion led to efficient inhibition of tumor growth." (PMID 31799200, 2019). "As a component of a complex network, TIGAR contributes to the metabolic adjustments that arise from either spontaneous or therapy-induced changes in tumor microenvironment." (PMID 30823646, 2019). "The analysis indicates that patients with high TIGAR expression in the tumor have a significantly (Logrank Test p-value = 0.00359)poor overall survival outcome compared to patients with low TIGAR expression in the tumor." (PMID 31508509, 2019). "In mouse intestinal adenoma models, TIGAR not only promoted regeneration of healthy tissue, but also supported tumor development." (PMID 30823646, 2019).
tumor (continued). "Transketolase-like protein 1 (TKTL1), an enzyme of the non-oxidative branch of the PPP, has been found to be upregulated in several tumor types, and is involved in tumor cell proliferation, sensitivity to ROS, and metabolic alteration mediated by TIGAR." (PMID 29805774, 2018). "The present study sought to investigate the expression pattern of TIGAR in NPC tumor tissues, and to analyze the consequences of TIGAR overexpression and knockdown on NPC cell growth and invasion." (PMID 25621025, 2015). "While the TAp73 isoform has recently been found to be able to increase PPP activity through direct activation of G6PDH to support tumor cell proliferation, it is possible that the regulation of TIGAR also contributes to this response." (PMID 24383451, 2014). "Here we discuss the activities of TIGAR described so far, and the potential consequences of TIGAR expression on normal and tumor cells." (PMID 24383451, 2014). "Conversely, the difference was significant between TIGAR expression in patients with respect to tumor size (≤3 or >3 cm), histological type (squamous or adenocarcinoma), differentiation degree (well or poor) and staging (N0 or N1)." (PMID 24363807, 2013). "A positive group displayed a widespread expression of TIGAR, either throughout the whole tumor sample or heterogeneously, with positive areas adjacent to TIGAR negative regions." (PMID 19763184, 2009). "Additionally, they have found that TIGAR expression levels are significantly correlated with advanced tumor stages, lymph node metastasis, and poor patient survival." (PMID 40277923, 2025). "Noteworthy is the significant elevation of TIGAR expression observed in various human tumors such as colon cancer, breast cancer, and glioblastoma, suggesting its potential as a valuable tool in early tumor diagnosis and precise treatment." (PMID 39091612, 2024). "Knockdown of TIGAR inhibits translocation of p65 into the nucleus in tumor cells." (PMID 38773142, 2024).